BRAF (B-Raf proto-oncogene, serine/threonine kinase)
Diseases named in the same sentence as BRAF in open-access papers (continued):
Sharing a sentence is not in itself a finding about the gene and the disease.
tumor (continued). "Studies examining the effects of sorafenib on sorafenib-resistant cell lines transfected with BRAF genes containing gatekeeper mutations indicated that the mutant B-Raf signaling was resistant to sorafenib, but sorafenib still inhibited tumor growth driven by the mutant B-Raf protein." (PMID 23085539, 2012). "Somatic BRAF mutation was present in one MMR-deficient tumor." (PMID 23049789, 2012). "Similarly, 6% (60 of 999) of tumor samples in the CRYSTAL study had a BRAF mutation, mainly in the setting of wild-type KRAS." (PMID 23202889, 2012). "We detected BRAF codon 600 mutations in 15 (25.4%) out of 59 tumor tissues." (PMID 22586484, 2012). "Furthermore, we estimated the frequency of BRAF mutant alleles in paired samples of primary tumour and recurrence or metastasis in three patients." (PMID 21224857, 2011). "As RAF mutations, in analogy with RAS mutations, may show tumor type specificity, we sequenced exons 11 and 15 in BRAF and the equivalent exons in ARAF (exons 10 and 13) and RAF1 (exons 11 and 14)." (PMID 21533174, 2011). "Among them are RAS and BRAF mutations, which rarely coexist in the same tumour." (PMID 21943101, 2011). "However, as would be expected, tumours containing KRAS/BRAF mutation are refractory to the therapeutic effects of anti-EGFR antibodies." (PMID 21698197, 2011). "Oncogenic mutations such as BRAF occur across diverse tumor types." (PMID 22039425, 2011). "However, right-side tumour location was more frequent (60%) in patients with BRAF mutation in all subtypes (P=0.0391)." (PMID 21285991, 2011). "While a recent study demonstrated an association between folate and CpG island methylation in normal colorectal tissue, how folate or other B vitamin intake influences CpG island methylation or BRAF mutation in tumor remains less well understood, and the literature data are somewhat limited." (PMID 21738611, 2011). "It has been proposed that the acquisition of a KRAS or BRAF mutation in a benign tumour might initiate the progression to an LMP tumour." (PMID 22163003, 2011). "CIMP-high CRCs were identified in 34 cases (13.9%), and were significantly associated with proximal tumor location, poorly differentiated carcinoma, mucinous histology, and high frequencies of BRAF mutation, MGMT methylation, and MSI-high compared to CIMP-low/negative carcinomas." (PMID 21827707, 2011). "The strong and independent associations of Wnt5a methylation with both MSI and BRAF V600E suggest that this event may be a marker of MSI/CIMP-high tumours, which seem to be a particularly favourable CRC subset in these studies." (PMID 21587258, 2011). "After a careful histopathological re-evaluation of the cases, three BRAF-mutated cases, originally placed in the control group, were reclassified as serrated adenocarcinomas because the serrated morphology was preserved in the tumour." (PMID 21457162, 2011). "CIMP-high carcinomas were found in 34 cases (13.9%) and were more frequently associated with proximal tumor locations, poorly differentiated histology, mucinous histology, BRAF mutation, MGMT methylation, and MSI-high compared to CIMP-low/negative carcinomas (P < 0.05)." (PMID 21827707, 2011). "Currently, we can speculate that when Cten expression is elevated in a tumour with KRAS/BRAF mutation, the association is likely to be causal." (PMID 21698197, 2011). "Manipulation of the MAPK signalling pathway could be a powerful means of treatment for tumours with BRAF mutations especially those resistant to TRAIL." (PMID 21738740, 2011). "ARUP Laboratories (Salt Lake City, UT) BRAF V600E Mutation Detection by PCR (2002498): This assay requires FFPE tumor tissue block or at least 3 unstained 5-micrometer (μm) slides of tumor tissue, and uses PCR with pyrosequencing to detect sequence variants in the BRAF gene." (PMID 20972475, 2010).
tumor (continued). "Moreover, our patients with MSI-H and BRAF-mutated tumours experienced significantly lower PFS (P=0.008) and OS (P=0.004) in comparison with those with MSI-H and BRAF wt primary tumours." (PMID 20485284, 2010). "In CRC tumours, BRAF mutations seem to occur more frequently in cases characterised by dMMR." (PMID 20485284, 2010). "In addition, PFS was 2.7 and 9.8 months for patients with BRAF-mutated and wt primary tumours respectively (P<0.001)." (PMID 20485284, 2010). "Hypermethylation assays and BRAF V600E mutation testing of tumor DNA can be used to distinguish an MSI-H tumor with absent MLH1 expression caused by hypermethylation of the MLH1 promoter from a tumor caused by a germ-line MLH1 mutation." (PMID 22933892, 2010). "In multivariate analysis, BRAF mutation and tumour grade were emerged as independent prognostic factors for reduced PFS (HR 2.8, 95% CI 1.4–5.7, P=0.004 and HR 2.0, 95% CI 1.3–3.2, P=0.001 respectively) and OS (HR 5.3, 95% CI 2.5–11.3, P<0.001 and HR 2.6, 95% CI 1.6–4.4, P<0.001 respectively)." (PMID 20485284, 2010). "Moreover, several studies suggest that the BRAF V600E mutation occurs much more frequently in MSI-H tumours in comparison with microsatellite stable (MSS) tumours (50 vs <5% respectively)." (PMID 20485284, 2010). "Approximately one third of pts included in this study had been included in previous reports.Of the 2 pts that responded to treatment with BRAF sequence variants, 1 had a p.Asp549Gly variant and the other had the p.Val600Glu variant, but at a low copy number in the tumor sample." (PMID 20972475, 2010). "Of the BRAF+ tumours, 25 out of 45 (56%) had BRAF mutations detected in the serum." (PMID 19861964, 2009). "In all of these cases, the tumour sample had been positive for a BRAF mutation." (PMID 19861964, 2009). "In the subgroup of 68 patients with KRAS 61 and 146 wild-type tumours, BRAF was mutated in 8 cases." (PMID 19603018, 2009). "We observed EGFR gene deregulation in 25 out of 36 primary tumours and 29 out of 36 metastases, K-Ras mutations in 16 out of 37 cancers and in 15 out of 37 metastases, BRAF mutations in 2 out of 36 cancers and 2 out of 36 metastases and PTEN loss in 8 out of 38 cancers and 12 out of 38 metastases." (PMID 19293803, 2009). "Of 94 tumour samples, 45 (47.9%) were found to be BRAF mutation positive (BRAF+)." (PMID 19861964, 2009). "Ultimately, this may make this tumour less aggressive, similar to what is observed in melanocytes where oncogenic BRAF mutations result only in naevi formation." (PMID 19603027, 2009). "In total, 70 BRAF mutations in tumour DNA were identified by ARMS (70 of 158 (44%))." (PMID 19861964, 2009). "One caveat of our system is that BRAFV600E could play a role in inducing DNA methylation only early in colorectal tumorigenesis, as BRAF mutations have been described at the earliest stage of tumor development." (PMID 20027224, 2009). "It is tempting to suggest that specific KRAS and BRAF mutation interaction may have a role to modulate gene expression profiling in specific tumor types (either MSS, or MSI, or CIN) toward a more aggressive phenotype." (PMID 19087308, 2008). "In addition, the mRNA expression of GGH and ECGF1 was associated with characteristic clinicopathological and molecular features of CIMP+, including proximal tumour site, TILs and BRAF mutation." (PMID 18414409, 2008). "In this study, 8 out of 9 KRAS/BRAF mutations were identified in early stage (stage I, II) tumours." (PMID 19018267, 2008). "Park and Giannini both studied BRAF mutation rate on 61 and 69 patients respectively and their results suggested 39.3% and 40% of the multifocal tumours may have arisen independently." (PMID 19055826, 2008). "Activating KRAS and BRAF mutations typically show mutant exclusivity in tumours." (PMID 19018267, 2008). "We detected a concurrent LKB1 mutation in one of the four BRAF mutant tumours." (PMID 18594528, 2008).
tumor (continued). "The relationship between the BRAF V600E mutation and aggressive tumour behaviour is controversial." (PMID 17179987, 2007). "Although early reports pointed at a lower BRAF mutation frequency in Chernobyl patients, recent evidence suggests that the BRAF mutation is associated with age and is more prevalent among older Chernobyl patients and/or among patients with longer latency tumours." (PMID 17712314, 2007). "This implies that abnormal accumulation of p-MAPK protein may be a critical event in the tumour progression of FDNs, independently of BRAF mutations." (PMID 16404419, 2006). "Although some molecular differences between flat-depressed neoplasias (FDNs) and protruding neoplasias (PNs) have been reported, it is uncertain if the BRAF mutations or the status of phosphorylated mitogen-activated protein kinase (p-MAPK) are different between theses two groups." (PMID 16404419, 2006). "Despite having only 9 MSI-/BRAF mutant and 5 CIMP-/BRAF mutant tumors, the results showed that associations between BRAF mutation and the morphological properties of tumor-infiltrating infiltrating lymphocytes, poor histological grade and mucinous phenotype were retained." (PMID 16403224, 2006). "The activating mutation of BRAF is known to play a role in tumour development." (PMID 14612909, 2003). "This case highlights the potential synergy between MAPK pathway inhibition and immunotherapy, suggesting that even short-course targeted therapy may favorably remodel the tumor microenvironment to enable durable disease control in high-risk MSI-H/BRAF-mutant mCRC." (PMID 42088195, 2026). "However, recent studies indicate that patients with PXAs exhibiting BRAF V600 mutations, present in 70% of tumours, may benefit from BRAF inhibitors such as vemurafenib or dabrafenib, though more studies are needed." (PMID 41340779, 2026). "In addition, these BRAF/MEKi-resistant cell lines displayed altered patterns of released immunomodulatory factors associated with pro-inflammatory and immunosuppressive functions, potentially contributing to tumor growth." (PMID 41550951, 2025). "BRAF mutations not only significantly influence the effects of anti–epidermal growth factor receptor monoclonal antibody treatment but are also closely associated with tumor invasiveness and metastasis, making them crucial indicators for evaluating disease progression and treatment prognosis." (PMID 40680189, 2025). "Notably, the clinical significance of BRAF mutations transcends tumor type." (PMID 41153346, 2025). "Furthermore, combining CALLY with molecular and genomic markers such as MSI, KRAS, and BRAF mutations, as well as circulating tumor DNA (ctDNA), could generate more comprehensive predictive models that align with the principles of precision oncology." (PMID 41479671, 2025). "Moreover, due to the intrinsic characteristics of BRAF mutations, BRAF-driven tumors in humans often exhibit aggressive phenotypes, which correlate with higher engraftment rates and faster tumor growth in vivo—two essential factors for successful PDX generation." (PMID 40507920, 2025). "Furthermore, multivariable analysis adjusting for tumor behavior may invalidate the association with BRAF and mortality, which underestimates its prognostic significance." (PMID 40149275, 2025). "Furthermore, BRAF mutations can induce genomic instability, increasing tumor heterogeneity." (PMID 40896440, 2025). "Consequently, although BRAF:p.V600E may indicate a higher-risk tumor profile, its value as a long-term prognostic marker currently remains uncertain." (PMID 40940966, 2025).
tumor (continued). "Furthermore, some studies suggest that a higher mutant allele frequency of BRAF V600E may correlate with more aggressive tumor behavior." (PMID 41458539, 2025). "Moreover, BRAF-associated signaling may further contribute to immune suppression and reduced tumor immunogenicity." (PMID 41562080, 2025). "Therefore, ATP-competitive inhibitors can either block or stimulate the MAPK pathway, depending on whether the tumor cells express wild-type BRAF or the BRAF V600E mutation." (PMID 40872623, 2025). "However, right-sided and high-grade tumours are more frequently associated with BRAF mutations." (PMID 40447784, 2025). "We could demonstrate the increase of mutational DNA fraction of H3F3A K27M in the CSF and plasma in patients with a tumor progression in the MR images and partially decreased levels for BRAF V600E mutation during targeted drug treatment with trametinib and dabrafenib." (PMID 39751690, 2025). "However, in multifocal PTCs where all foci harbor mutual BRAF p.V600E mutation, additional clonality studies are warranted to clarify whether these represent truly multicentric tumors or intraglandular tumor spreading." (PMID 40111709, 2025). "Additionally, for patients with advanced solid tumors harboring a confirmed BRAF V600 mutation, treatment recommendations should be refined based on the specific tumor type and molecular pathological characteristics, such as the presence of MSI-H or high PD-L1 expression." (PMID 39529955, 2024). "The BRAF mutational status was determined based on a next-generation sequencing panel in 56.7% of cases, on a targeted multiplex PCR in 33.8% of cases, on circulating tumor DNA in 2.0% of cases, and with an unknown or another method in 7.5% of cases." (PMID 39255538, 2024). "Cells with a BRAF mutation could exist rarely in a chimeric state in the primary tumour." (PMID 39139611, 2024). "Numerous studies on colorectal cancer have highlighted the significance of tumor lymphocytic reaction and T-cell subpopulations as substantial prognostic biomarkers, even following adjustments for stage, lymph node count, and well-established prognostic indicators like BRAF mutation." (PMID 39682117, 2024). "In addition, in the four dogs that underwent both the cytological and histopathological exams, the BRAF V595E mutation was detected in both the liquid and tumor tissue samples in two cases, while the other two dogs did not harbor the BRAF V595E mutation in either the liquid or tissue samples." (PMID 39272320, 2024). "Therefore, BRAF mutation could promote the genesis of tumor melanocyte clones that would take on the biomolecular characteristics required to generate CNMs." (PMID 39099686, 2024). "Moreover, BRAF mutations may lead to tumor cell resistance to chemotherapeutic drugs, as autophagy can protect cancer cells from the cytotoxic effects of chemotherapy." (PMID 39529955, 2024). "Our study reported that BRAF (V600E) mutated NMs have a higher number of CNMs at the periphery of the mass, suggesting that the accumulation of genetic mutations in tumor cells could promote the creation of clones of cells that can aggregate and migrate by invading the dermis." (PMID 39099686, 2024). "Therefore, BRAF mutations may lead to excessive proliferation of tumor cells and participate in the regulation affecting epithelial-mesenchymal transition, which in turn influences the behavior of immune cells." (PMID 39529955, 2024).
tumor (continued). "In the clinics, resistance to targeted therapy may depend on the drug-resistant phenotype of preexisting tumor cell subpopulations (intrinsic resistance) or occur via de novo mutations that render cancer cells permanently refractory to BRAF/MEKi treatment (acquired resistance)." (PMID 38755661, 2024). "In addition, BRAF mutations have a significant impact on survival, portending a poor prognosis relative to RAS mutations; although BRAF is closely related to primary tumor location, BRAF mutations remain an independent predictor of poor outcomes irrespective of site." (PMID 38651190, 2024). "Furthermore, some papers have suggested that due to the tumor's resistance to cytotoxic chemotherapy, patients with this mutation may benefit from BRAF inhibitors." (PMID 37600581, 2023). "Mutated BRAF gene may be a key oncogenic driver in promoting carcinogenesis and tumour progression." (PMID 37542343, 2023). "Indeed, for the patient carrying the p.T599dup mutation, a liquid biopsy approach was available, demonstrating that longitudinal monitoring of the BRAF mutant allele fraction by liquid biopsy is a useful tool to identify tumor progression and track disease evolution." (PMID 37569660, 2023). "However, additional studies using a broader range of cell lines, including primary tumor cell lines with BRAF variants, are needed to determine whether Dicer-mediated ADSL expression exerts a similar effect on these cells." (PMID 37976135, 2023). "Moreover, STK11 is associated with diminished immunotherapy response; and BRAF variants, which are associated with a higher tumor burden, may make tumors vulnerable to immunotherapy." (PMID 37152678, 2023). "Notably, this study also showed that immature thyroid cells in the developing gland possessed much higher tumorigenic potential than adult BRAF mutant follicular epithelial cells, suggesting that tissue maturity profoundly influenced tumor cell behavior and ultimately mutation penetrance." (PMID 37534159, 2023). "In this study, using paired tumor and surrounding normal tissue from the same patients, on a genome-wide scale we tried to identify (a) any association between BRAF mutation and DNA promoter methylation, and (b) if the molecular findings may provide a basis for therapeutic intervention." (PMID 36975440, 2023). "In conclusion, the low-risk group had a higher BRAF mutation fraction and stronger antitumor immune responses, suggesting that risk groups may comprehensively reflect both tumor genomic information and anti-tumor immune microenvironment." (PMID 35903095, 2022). "In fact, the loss of function caused by NF1 gene mutation may prolong the activation time of the Ras dependent signal pathway, and, in addition, may cause abnormal signal expression which is different from the classic BRAF mutation, resulting in tumor dedifferentiation." (PMID 35865459, 2022). "In addition to the MSI status, the immune profile might be an important factor in explaining the diverse tumor biology of BRAF-MT tumors, and the incidence of BRAF mutation was lower, with 5.3% compared to previous reports." (PMID 35625987, 2022). "The number and locations of tumors, quadrant of tumors, regularity of tumor margins, presence of blood flow signals, presence of posterior echo attenuation, presence of calcification, histological grade, molecular typing, and mutations of BRAF, ATM, and PALB2 were irrelevant factors (P > 0.05)." (PMID 35255911, 2022). "Therefore, BRAF mutation represents strong tumor invasiveness." (PMID 36380085, 2022).